SIRT3 (sirtuin 3)
Diseases named in the same sentence as SIRT3 in open-access papers (continued):
Sharing a sentence is not in itself a finding about the gene and the disease.
diabetes (continued). "Consistent with the results of this study, others have shown that diabetes and obesity reduce the expression of Sirt1, Sirt2, Sirt3, and Sirt6." (PMID 38134189, 2023). "Taken together, these data demonstrate that SIRT3 can rescue hippocampal neurons from diabetes-induced injury." (PMID 37481555, 2023). "Omarigliptin treatment ameliorated diabetes-induced mitochondrial dysfunction and oxidative stress, and SIRT3 was required for the effects of Omarigliptin." (PMID 35389830, 2022). "In the mouse model of diabetes, salidroside is known to confer protection by increasing SIRT3 expression and translocation to mitochondria, promoting MnSOD activity, thereby reducing oxidative damage observed in diabetic patients cardiomyopathy." (PMID 35369299, 2022). "Acacetin alleviates diabetes-accelerated atherosclerosis by preserving mitochondrial function via activating Sirtuin1 (Sirt1)/Sirtuin3 (Sirt3)/AMP-activated protein kinase (AMPK) pathway." (PMID 36299901, 2022). "SIRT3, the main mitochondrial deacetylase, regulates multiple metabolic pathways and its expression is reduced in diabetes." (PMID 36009329, 2022). "As expected, CO potentiated the downregulation of pAMPK/AMPK, PGC1α, and SIRT3 expressions in diabetes." (PMID 36008962, 2022). "Given that FOXO3a and SIRT3 are involved in the development of diabetes, we investigated how Omarigliptin affected their gene expressions in brain hippocampus tissues." (PMID 35389830, 2022). "Another important finding of the present study is that the downregulated SIRT3/FOXO3a pathway caused by NOX activation in turn results in an increased generation of reactive oxygen species, aggravating the diabetes-related ventricular remodeling." (PMID 36139819, 2022). "Yet another known SIRT3 activator, Salidroside, extracted from Rhodiola rosea has been shown to protect against cardiac dysfunction in animal models of diabetes and myocardial infarction (MI)." (PMID 35369299, 2022). "We showed that Omarigliptin treatment ameliorated diabetes-induced mitochondrial dysfunction in the brain, and the expression of SIRT3 was required for the effect of Omarigliptin." (PMID 35389830, 2022). "Compared to the control group, the expressions of SIRT3 showed a decreased trend in the diabetes group (p = 0.09), and apocynin treatment significantly reversed SIRT3 expressions (p < 0.01)." (PMID 36139819, 2022). "Although 129S mice develop features of metabolic syndrome with lower severity compared to some other strains, 129S Sirt3 KO mice are extremely useful in studying the role of FA oxidation in diabetes, steatosis, and life span." (PMID 33924115, 2021). "SIRT3 in skeletal muscles regulates oxidative stress, insulin resistance, and energy homeostasis, especially in type 2 diabetes mellitus." (PMID 33614337, 2021). "Polydatin, a naturally occurring small molecule, has been proposed to alleviate high glucose-induced cardiac dysfunction by endorsing autophagy flux and improving mitochondrial bioenergetics through SIRT3 activation in the heart of diabetes mice." (PMID 34071497, 2021). "The expression of SIRT3 in skeletal muscle cells is reduced during diabetes, and SIRT3 knockout mice exhibit increased oxidative stress, reduced oxygen consumption and impaired insulin signaling in their muscle cells." (PMID 33806509, 2021). "We have previously reported the cardioprotective effect of garlic and resveratrol against diabetes-induced oxidative stress via activation of Sirt1 and Sirt3, respectively." (PMID 33668369, 2021). "Study had indicated that TGR5 played a protective role in nephropathy in obesity and diabetes via promoting SIRT3 expression." (PMID 33298860, 2020). "Our results suggested that acacetin reduced vascular endothelial injury induced by high glucose and attenuated diabetes-accelerated atherosclerosis by Sirt1-mediated activation of Sirt3/AMPK signals." (PMID 33519472, 2020).
diabetes (continued). "Changes in sirtuin-3 expression have a profound impact on the pathophysiology of several diseases, including metabolic syndrome, diabetes, and the aging processes." (PMID 33519447, 2020). "Apigenin ameliorates the diabetes-induced renal tubular injury by reducing mitochondrial oxidative stress via CD38-mediated Sirt3 activation." (PMID 32507768, 2020). "Although a recent study suggests that SIRT3 is dispensable in adipocyte metabolism and obesity-induced metabolic complications 157, SIRT3 in fact is important in obesity and diabetes." (PMID 32724473, 2020). "Activation of SIRT3 can also regulate skeletal muscle metabolism and activate insulin signaling to improve diabetes." (PMID 32724473, 2020). "It has been proved that SIRT3 is required for the beneficial effects of caloric restriction to reduce the intracellular ROS levels in aging, obesity and diabetes." (PMID 32722262, 2020). "For example, exendin-4, an anti-diabetes drug that has been used to control fasting blood glucose, upregulated SirT3 activity in a mouse model of myocardial ischemia-reperfusion injury." (PMID 32721927, 2020). "The NAD+/NADH ratio and mitochondrial anti-oxidative properties mediated by Sirt3 activation are restored by apigenin, leading to the amelioration of diabetes-induced renal injury, particularly renal tubular injury." (PMID 32507768, 2020). "As for diabetes, it has been shown that, in kidney biopsies from patients with diabetic nephropathy, Sirt3 mRNA expression is downregulated and treatments that aim to reduce oxidative stress are renoprotective in mice with DN16." (PMID 32439965, 2020). "Transmission electron microscopy showed that the mitochondrial cristae in the skin of SIRT3 KO mice with diabetes became fewer, but fragmented and disordered." (PMID 32119761, 2020). "In an in vitro model of diabetes, sirtuin-3 overexpression protected proximal tubular cells against high glucose-induced oxidative stress by enhancing the expression of antioxidant genes superoxide dismutase (SOD) and catalase." (PMID 33519447, 2020). "The study showed that DHY improved endothelium-dependent relaxation of thoracic aorta in wild type (WT) diabetic mice, which was abolished in SIRT3-/- mice with diabetes." (PMID 32933152, 2020). "In this study, SIRT1 and SIRT3 expression was decreased in T1D and T2D, suggested their roles in the pathogenesis of diabetes." (PMID 30736780, 2019). "All these data clearly highlight the protective role of SIRT3 in maintaining β-cell function in lipotoxic conditions, such as diabetes." (PMID 31557786, 2019). "We observed a slight positivity of SIRT-3 in two of nine diabetic patients with metabolic syndrome and in four of eight patients with only diabetes." (PMID 30917505, 2019). "Our data is contrasting with previous findings where the content of SIRT3 was heavily decreased in diabetic pancreas and lung, possibly the alterations in SIRT3 in diabetes are likely tissue dependent." (PMID 29949946, 2018). "Downregulation of SIRT3 is a key component of metabolic syndrome, a precondition for obesity, diabetes and cardiovascular diseases." (PMID 30510203, 2018). "Deliberating the role of SIRT-3 in mitochondrial energetics and mitochondrial dysfunction in diabetes, we thought to find out the missing link between SITR3 and mitochondrial function in the diabetic heart." (PMID 30487434, 2018). "Metformin, a common drug for diabetes treatment, was found to modulate the appearance of atherosclerosis and reduce vascular events by increasing SIRT3 expression." (PMID 29643974, 2018). "The mitochondrial lysine deacetylase Sirtuin 3 (Sirt3) reverses this modification with benefits reported in diabetes, obesity, and aging." (PMID 28249157, 2017). "Down-regulation of SIRT3 results in several age-related diseases including cancer, diabetes, cardiac pathologies and neurodegenerative disorders." (PMID 27352213, 2016).
diabetes (continued). "In this study, we further investigated the direct role of Sirt3 in APLN-induced angiogenesis in post-MI model of diabetes." (PMID 25311234, 2015). "Our present study provides direct evidence that Sirt3 has a critical role in apelin-induced myocardial angiogenesis in ischaemic heart of diabetes." (PMID 25311234, 2015). "A potential role of targeting SIRT3 in diabetes was supported by a recent study showing that overexpression of SIRT3 can mitigate palmitate-mediated pancreatic β cell dysfunction." (PMID 26370974, 2015). "Wild-type (WT) and Sirt3 knockout (Sirt3KO) mice were induced into diabetes by i.p. streptozotocin (STZ)." (PMID 25311234, 2015). "Wild type and Sirt3 knockout (Sirt3 KO) mice were induced into diabetes by intra-peritoneal (i.p.)Streptozotocin (STZ)." (PMID 29167823, 2015). "Understanding SIRT3's biochemical function and regulation in the liver under conditions of caloric excess may potentially increase our understanding of the normal aging process and diseases associated with aging, such as diabetes, fatty liver disease, or cancer." (PMID 21386135, 2011). "With therecent discovery of BAT in humans, there arenow new opportunities to explore the role of SIRT3 in diabetes and obesityresearch." (PMID 20157566, 2009). "Additionally, as a comorbidity of diabetes, clarifying the mechanism of SIRT3 in diabetes is of great significance for halting the further progression of neurological damage." (PMID 40969935, 2025). "Ultimately, SIRT3 may represent a convergent therapeutic target for mitigating the multiorgan sequelae of diabetes via its dual roles in mitochondrial regulation and oxidative stress control." (PMID 40860195, 2025). "This suggests that diabetes may hinder mitochondrial regeneration by inhibiting the SIRT1/SIRT3-PGC-1α-NRF1-TFAM signaling pathway, thereby exacerbating cerebral ischemia-reperfusion injury in rats." (PMID 40969935, 2025). "As previous study has shown, the decreased expression of Sirt3 in oocytes of the mice with diabetes may participate in meiosis disorder and ROS accumulation." (PMID 38653987, 2024). "Furthermore, Nissl staining demonstrated that diabetes significantly reduced CA1 hippocampal neurons which was reversed by SIRT3 overexpression." (PMID 37481555, 2023). "Similarly, in mice with streptozotocin (STZ, 60 mg/kg, ip)-induced diabetes mellitus, SIRT3 deletion resulted in the upregulation of inflammatory mediators such as NLRP3, caspase-1 p20, and IL-1 β, ultimately exacerbating diabetic cardiomyopathy." (PMID 37196115, 2023). "As synaptic plasticity provides a cellular basis for learning and memory, we next tested whether up-regulation of SIRT3 could improve diabetes-induced cognitive deficit." (PMID 37481555, 2023). "Therapeutic strategies targeting post-translational modification of this protein have shown a pivotal potential in the treatment of diabetes, as well as showing the modulation of oxidative stress via SIRT3 has clearly been effective in this multifaceted disease." (PMID 37372041, 2023). "Furthermore, it rescued myocardial energetic dysfunction in diabetes by activating SIRT3-mediated deacetylation of mitochondrial proteins and alleviated lipid-induced hepatic IR by activating SIRT3-mediated lipophagy." (PMID 36466390, 2022). "Further analysis showed that acacetin suppressed atherosclerosis aggravated by diabetes may be mediated by activating the Sirt1/Sirt3/AMPK signaling pathway to protect mitochondrial function." (PMID 35677446, 2022). "There is no extra benefit for combining Sirt1 and Sirt3 activators for the treatment of diabetes and associated cardiac complication." (PMID 33668369, 2021). "Sirt3 may regulate ROS production and might be involved in β-cell apoptosis, which plays an important role in the progression of type 2 diabetes mellitus (T2DM)." (PMID 34249264, 2021).
diabetes (continued). "In our laboratory, we have investigated crucial molecules that provide endothelial cell stability integrity, such as endothelial SIRT3, which is an essential mitochondrial protein and maintains the balance of fuel preference between healthy and damaged endothelial cells in diabetes." (PMID 34451848, 2021). "In this study, Elabela treatment was found to have profound protective effects against diabetes‐induced cardiac oxidative stress, inflammation, fibrosis and apoptosis; these protective effects may depend heavily upon SIRT3‐mediated Foxo3a deacetylation." (PMID 33244875, 2021). "To investigate the mechanisms of MSCs against diabetes-induced lung fibrosis, we hypothesized that the capability of MSCs might mainly result from upregulating the Sirt3/SOD2 signaling pathway." (PMID 32089781, 2020). "It was suggested that SIRT3 pathway was impaired in the skin tissues of patients with diabetes." (PMID 32119761, 2020). "In addition to the diet-induced obese mouse model, SIRT3 also plays a role in the pathogenesis of streptozotocin (STZ)-induced diabetes." (PMID 32722262, 2020). "The specific activation of sirtuin-3 is therefore effective in reducing diabetes-induced oxidative stress and providing protection for podocytes and more generally the glomerulus against diabetes-induced damage." (PMID 33519447, 2020). "Diabetes-related decrease in SIRT3 activity may be improved by the presence of resveratrol—one of the AMPK activators." (PMID 33070285, 2020). "Findings from earlier studies revealed that diabetes may downregulate the expression of Sirt3 and disrupt the Ang-1/Tie-2 signaling cascade to enhance myocardial infarction injury via regulation of myocardial vascular maturation and angiogenesis." (PMID 32411318, 2020). "Since in diabetes, SIRT3 expression in muscles may be significantly reduced, AMPK activation becomes even more crucial in order to modulate OGG1 activity." (PMID 33070285, 2020). "SIRT3 KO mice with diabetes exhibited mitochondria swelling with greater volume." (PMID 32119761, 2020). "Recently, several studies have determined that overexpressing Sirt3 through preconditioning or genetic technology was able to activate Parkin-dependent mitophagy, which eliminated superfluous and damaged mitochondria in cardiomyocytes during diabetes." (PMID 32256959, 2020). "In diabetes pathogenesis, Sirt3 plays a protective role and involves a variety of stress responses." (PMID 32089781, 2020). "In addition, IL-1β and TNFα treatments, which mimic the inflammation condition of diabetes, decreased SIRT3 expression in a mouse insulin-producing β cell line (INS1)." (PMID 32722262, 2020). "We previously showed that mitochondrial oxidative stress in the kidneys of Zucker diabetic fatty rats is associated with a decreased intracellular NAD+/NADH ratio and NAD+-dependent deacetylase Sirt3 activity, and increased expression of the NAD+-degrading enzyme CD38." (PMID 32507768, 2020). "Therefore, in the present article, we discuss the role of SIRT1, SIRT3, and PA on β-cell function and on diabetes." (PMID 31557786, 2019). "Thus, designing drugs to enhance SIRT1 and SIRT3 expression and their activity would be useful to protect patients with diabetes and HT against the damaging effect of oxidative stress." (PMID 30736780, 2019). "Furthermore, our research group published a work showing high expression of SIRT-3 in HCC patients with type-2 diabetes mellitus (T2DM) and in those undergoing chronic treatment with metformin." (PMID 30917505, 2019). "Therefore, we focused on Sirt3 activity toelucidate the mechanism of mitochondrial oxidative stress in the diabetic kidney." (PMID 29897845, 2018). "Therefore, we believe that measures to enhance SIRT3 expression and its activity would be useful to protect women against the development of diabetes." (PMID 29435415, 2018). "SIRT3 can prevent and even reverse diabetes-induced retinal, skeletal, and cardiac damage." (PMID 29643974, 2018).
diabetes (continued). "We hypothesized that SIRT-3 has a crucial role in regulating the mitochondrial function in diabetic heart through regulating TFAM and thus targeting SIRT3 could be a useful approach to overcome cardiac complications in diabetes." (PMID 30487434, 2018). "Due to the close correlation between these proteins (SIRT and UCP) and mitochondrial oxidative phosphorylation, we hypothesized that M. oleifera may exert a protective effect against the development of diabetes through regulatory effect of SIRT3 and UCP2." (PMID 29949946, 2018). "SIRT3 is also involved in metabolic disease such as diabetes." (PMID 27352213, 2016). "Similar to failing hearts, SIRT3 downregulation may also contribute to myocardial mitochondrial dysfunction and oxidative stress in diabetes, but may also contribute to reduced capillary density in diabetic hearts." (PMID 27790619, 2016). "Moreover, we have explored the potential mechanisms by which Sirt3 regulates APLN-induced myocardial angiogenesis in diabetes." (PMID 25311234, 2015). "It has been reported, in fact, that the expression of mitochondrial SIRT3 may be up-regulated in caloric restriction and down-regulated in obesity and diabetes." (PMID 21906315, 2011). "Some interactions with a nominal p≤0.01 were found between sex and SNPs in the UCP1 and UCP3 gene; between smoking, diabetes, hypertension and SNPs in UCP5 and SIRT5; and between SNPs in the UCP5 gene and the UCP1, SIRT1, SIRT3, SIRT5, and SIRT6 genes in association with plaque phenotypes." (PMID 22087257, 2011). "Thus, we hypothesized that luteolin may alleviate post-CA/CPR myocardial injury in diabetes by inhibiting necroptosis through activation of the Sirt3 signaling pathway." (PMID 40635895, 2025). "Therefore, the present study was carried out to investigate whether luteolin alleviates myocardial I/R injury following CA/CPR in diabetes, specifically through Sirt3-mediated inhibition of necroptosis." (PMID 40635895, 2025). "Furthermore, a deeper understanding is required regarding the mechanisms driving the downregulation of SIRT3 in the context of diabetic osteoporosis, as well as its distinct functions across different diabetes subtypes, highlighting the need for meticulous further research." (PMID 40025004, 2025). "However, whether SIRT3 exerts a critical role in MAM coupling and diabetes-associated cognitive dysfunction remains elusive." (PMID 37481555, 2023). "Next, we determined whether the NAF1L2/SIRT3 axis had an impact on BCAA catabolism in diabetes." (PMID 37993768, 2023). "However, whether an HG-induced reduction in SIRT3 contributes to the impairment of hypoxic signaling in diabetes remains unexplored." (PMID 37048134, 2023). "In conclusion, here we have shown that SIRT3 plays a crucial role in the pathogenesis of DN and that its specific activation through honokiol reduces diabetes-induced oxidative stress and protects podocytes and, generally, the glomerulus from diabetes-induced damage." (PMID 32439965, 2020). "Thus, Sirt3 may serve as an important target for inhibiting the tissue fibrosis induced by diabetes via regulating various stress responses such as inflammation, oxidative stress, apoptosis, autophagy, and ER stress." (PMID 32089781, 2020). "Moreover, since it is well established that palmitate-induced endoplasmic reticulum (ER) stress in β-cells promotes apoptosis and diabetes, a significant reduction in mRNA expression of several factors commonly activated by ER stress in overexpressing SIRT3 cells was reported." (PMID 31557786, 2019). "Therefore, the evidence presented here on the effects of SIRT3 overexpression in pancreatic β cells may contribute to new and effective therapies for the treatment of diabetes." (PMID 25915406, 2015). "Finally, low Sirt1 and Sirt3 expression, due to high NADH/NAD, may decrease Foxo-1 and MnSod expression, causing oxidative stress that results in cell death/aging or diabetes." (PMID 26558285, 2015).